IL22 (interleukin 22)
Diseases named in the same sentence as IL22 in open-access papers (continued):
Sharing a sentence is not in itself a finding about the gene and the disease.
clostridium difficile infection (3 papers, 2022 to 2024). Symptomatic infection due to the spore-forming bacterium clostridium difficile. "A previous study found that IL-22 plays a protective role during Clostridium difficile infection by modulating the expression of complement component C3, which, in turn, enhances phagocytosis." (PMID 38557196, 2024). "Similarly, it has also been shown that Ffar2-mediated potentiation of ILC3 activity to produce IL-22 was beneficial to ameliorating Clostridium difficile infection." (PMID 38238790, 2024).
colorectal tumors (3 papers, 2019 to 2023). "Of note, the ablation of the IL-22 pathway via an endogenous antagonist, IL-22-binding protein, suppressed tumorigenesis in a genetic model and another study has reported that blocking IL-22 which was locally produced by innate lymphoid cells inhibits colorectal tumors in the mouse." (PMID 31935914, 2020). "Interleukin-22 (IL-22) is a critical immune defence cytokine that maintains intestinal homeostasis and promotes wound healing and tissue regeneration, which can support the growth of colorectal tumours." (PMID 31770366, 2019).
cutaneous leishmaniasis (3 papers, 2015 to 2025). Leishmaniasis affecting the skin. "Taken together, these studies demonstrate that during cutaneous leishmaniasis, IL-22 can play a previously unappreciated role in controlling leishmania-induced immunopathology." (PMID 26285207, 2015). "IL-22 protects against tissue damage during cutaneous leishmaniasis." (PMID 40067811, 2025). "In L. major- or L. braziliensis-infected mice the production of IL-22 decreases the lesion size without any effect on parasite load, indicating that IL-22 is more associated with the control of inflammation and wound healing than with parasite control in cutaneous leishmaniasis." (PMID 32023240, 2020). "Thus, one role of IL-22 during cutaneous leishmaniasis may be to promote wound healing capabilities of keratinocytes by regulating the expression of keratins involved in migration and differentiation." (PMID 26285207, 2015). "Thus, we hypothesize that in more severe forms of cutaneous leishmaniasis, as often seen following L. braziliensis infection, IL-22 might be induced to ensure that even more severe disease does not develop." (PMID 26285207, 2015). "Our results uncover a previously unknown role for IL-22 during cutaneous leishmaniasis." (PMID 26285207, 2015).
cutaneous T-cell lymphoma (3 papers, 2016 to 2024). "As feedback, benign T cells in cutaneous T-cell lymphoma express interleukin 22 (Il-22), which may foster the expression of chemokine ligand 20 (CCL20) expression via STAT3 activation." (PMID 36765704, 2023). "Also, recent study suggests an IL-22/STAT3/CCL20 signal cascade in cutaneous T-cell lymphoma." (PMID 26901187, 2016).
cyst (3 papers, 2021 to 2026). A sac-like closed membranous structure that may be empty or contain fluid or amorphous material. "Immunized animals showed significant reductions in intestinal trophozoite burden and faecal cyst shedding at 7, 14, and 21 days post-infection, accompanied by increased serum IL-17F and IL-22." (PMID 42290664, 2026). "Analyzing the 3D-cyst model, IL-22 induced multi-lumen and aberrant cysts, and altered the localization of cell polarity proteins." (PMID 33912578, 2021).
dengue (3 papers, 2016 to 2022). "In a mouse model of dengue, IL-22-/- deficient mice were more susceptible to DENV infection than WT mice, suggesting a protective role for this cytokine." (PMID 33322218, 2020). "Treatment of dengue-infected IL-22 deficient mice with anti-IL-17 antibodies reverts to the disease phenotype, confirming an antagonist function for both cytokines in this model of dengue infection." (PMID 33322218, 2020). "It has been shown in dengue mouse models that both IL-22 and IL-17 are associated with severe clinical disease and in particularly liver injury." (PMID 27391896, 2016). "It has been shown that in dengue mouse models, that both IL-22 and IL-17 were associated with severe clinical disease, and particularly liver injury." (PMID 27391896, 2016). "Although this study shows that IL-17 produced by γδT cells was pathogenic and IL-22 produced by natural killer cells played a protective role, another study in a dengue mouse model showed that early infiltration by NK cells was associated with apoptosis of liver cells." (PMID 27391896, 2016). "In our study, we found for the first time that DENV infection in humans is associated with higher IL-22 serum levels in DHF patients relative to DF patients, which suggests an important role for IL-22 in terms of regulating the inflammatory effects of IL-17 during dengue infection." (PMID 33322218, 2020). "Studies done on IL-22 knock out mice have shown that IL-17 plays an important role in the pathogenesis of dengue and also stimulated neutrophil recruitment to the liver, which was found to associate with the severity of liver damage." (PMID 27391896, 2016). "In addition, there was an increase in IL-22 serum levels in the febrile phase of primary dengue patients relative to HC, (p = 0.009)." (PMID 33322218, 2020).
diarrhoea (3 papers, 2021 to 2026). "These IL-22-mediated responses limited V. cholerae intestinal colonization and protected mice from diarrhoea and death." (PMID 42236988, 2026). "Prior to reaching the endpoint, the Il22−/− mice developed severe diarrhoea, characterised by visibly loose stool and faecal matter adhering to the cage walls." (PMID 41361166, 2025). "Both Il22+/+ and Il22−/− mice showed increased faecal trait scores and water content upon C. rodentium infection, indicating diarrhoea, but values were significantly higher in Il22−/− mice at 6 dpi." (PMID 41361166, 2025).
End Stage Liver Disease (3 papers, 2012 to 2024). Final stage of a liver disease when the liver failure is irreversible and LIVER TRANSPLANTATION is needed. "Interleukin-22 (IL-22), recently identified as a crucial parameter of pathology in experimental liver damage, may determine survival in clinical end-stage liver disease." (PMID 22967278, 2012). "The prognostic relevance of elevated IL-22 levels in patients with end-stage liver disease has not been characterized so far." (PMID 22967278, 2012).
endometriosis (3 papers, 2024 to 2025). The growth of functional endometrial tissue in anatomic sites outside the uterine body. "This raises the possibility that endothelial and glandular epithelial cells are less exposed to IL-22 in the eutopic endometrium of people with endometriosis." (PMID 40303843, 2025). "IL22 in the setting of endometriosis promotes proliferation of ESCs via secretion of CCL2 and IL-8." (PMID 38999962, 2024).
Hashimoto thyroiditis (3 papers, 2014 to 2024). An autoimmune disorder caused by the production of autoantibodies against thyroid tissue. "Although IL-22 is more often associated with Graves’ disease, recent research suggests its possible role in Hashimoto’s thyroiditis." (PMID 38999993, 2024). "Our results suggested that rs11611206 polymorphism of IL-22, including both allele G and genotype GG, may be a genetic risk factor for autoimmune hypothyroidism in HT." (PMID 28839453, 2017). "When analyzing the importance of IL-22 in the pathogenesis of Hashimoto’s thyroiditis, it is worth paying attention to its relationship with the number of antibodies against thyroid peroxidase." (PMID 38999993, 2024). "However, the role of IL-22+ and IL-17A+ CD4+ T cells in the pathogenesis of Hashimoto’s thyroiditis (HT) is not fully understood." (PMID 24404171, 2014).
head and neck squamous cell carcinoma (3 papers, 2020 to 2022). A squamous cell carcinoma that arises from any of the following anatomic sites: lip and oral cavity, nasal cavity, paranasal sinuses, pharynx, larynx, and salivary glands. "Investigating the IL-22 functionality in a head and neck squamous cell carcinoma (HNSCC) model, a comparison of a second-generation CAR T cells with fourth-generation CAR-T cells merged with this cytokine was done." (PMID 36172343, 2022). "CAR-MUC1-IL22 T cells secreting IL-22 enhance recognition and cytotoxic ability against head and neck squamous cell carcinoma." (PMID 32423475, 2020).
Listeria monocytogenes infection (3 papers, 2011 to 2016). "On the other hand, IL-22 is negligible for the host defense to Mycobacterium tuberculosis and Listeria monocytogenes infection." (PMID 26867135, 2016). "However in this infection model it remains unclear if IL-22 is induced and the absence of any effect of IL-22-deficieny on adaptive immunity might be due the lack of IL-22-induced signalling during Listeria monocytogenes infection." (PMID 27311945, 2016).
lymphopenia (3 papers, 2021 to 2025). Reduction in the number of lymphocytes. "Thus, although IL-6 can promote the differentiation of Th17 cells and the secretion of IL-17A and IL-22, low levels of IL-17A and IL-22 are more likely due to lymphopenia." (PMID 34692846, 2021).
mastitis (3 papers, 2017 to 2024). Inflammation of breast tissue during lactation or postpartum due to an obstructed duct or infection. "We developed a targeted mastitis gene therapy protocol using the yak IL-22 gene as an anti-inflammatory agent instead of antibiotics to suppress mastitis caused by S. aureus." (PMID 39453107, 2024). "Sufficient expression of IL-22 effectively inhibited the high expression of inflammatory factors caused by Staphylococcus aureus, reduced the symptoms of mammary gland histopathology, and alleviated mastitis." (PMID 39453107, 2024). "Under the action of IL-22, the intestinal flora of mastitis mice also changed, the abundance of intestinal Bacilli, Prevotellaceae, and Alloprevotella in mice increased after treatment, and the pathogenic bacteria decreased." (PMID 39453107, 2024). "This indicates that the yak IL-22 protein, as an internal cytokine, has few toxic side effects and can treat mastitis safely and effectively." (PMID 39453107, 2024). "The yak IL-22 gene is highly conserved in cattle and can be used as a widespread mastitis therapy gene." (PMID 39453107, 2024). "The production of the signature cytokines IL-17A, IL-17F, and IL-22 in milk over the course of S. uberis, E. coli, and S. aureus mastitis suggest that innate type 3 immunity is part of the natural immunity to mastitis." (PMID 35214754, 2022). "This discovery made it simpler to apply the yak IL-22 gene to bovine mastitis." (PMID 39453107, 2024). "In this study, IL-22 was selected as a candidate drug for the treatment of bovine mastitis, and its anti-inflammatory repair effect was used to treat mammary tissue injured by mastitis." (PMID 39453107, 2024). "However, the in vivo and in vitro antibacterial activity of yak Interleukin-22 (IL-22) and its application in mastitis caused by Staphylococcus aureus have not been reported." (PMID 39453107, 2024). "However, the antimicrobial activity of IL-22 in yaks and its application in Staphylococcus aureus (S. aureus)-induced mastitis have not been reported." (PMID 39453107, 2024).
Opportunistic infection (3 papers, 2020 to 2024). An infection that is caused by a pathogen that would generally not be able to cause an infection in a host with a normal immune system. "Since impairment of IL-22 is likely to be associated with suppression of several proteins involved in mucosal defense, it is not unlikely that this may pave the ground for secondary, opportunistic infections and increased sensitivity to environmental stressors in the aftermath of a SGPV-infection." (PMID 33013908, 2020).
pancreatic ductal adenocarcinoma (3 papers, 2015 to 2022). An infiltrating adenocarcinoma that arises from the epithelial cells of the pancreas. "Elated expression of systemic IL-22 positively correlates to poor prognosis of patients undergoing resection for pancreatic ductal adenocarcinomas." (PMID 33042126, 2020). "IL-22 mediated ductal adenocarcinomas of the pancreas expresses elevated level of IL-22 and IL-22R1, concomitant with enhanced MMP production and invasion of lymph nodes." (PMID 33042126, 2020). "In pancreatic ductal adenocarcinoma, interleukin-22 (IL-22)-mediated activation of STAT3 promotes tumorsphere formation and invasion, and it increases the expression of pluripotency-associated transcription factors including SOX2 and NANOG as well as EMT markers." (PMID 36118530, 2022).
papillary thyroid cancer (3 papers, 2015 to 2022). "Recently, a case-control study found that the IL-22 -429 C/T gene polymorphism might be associated with the risk and multifocality of papillary thyroid cancer." (PMID 26598081, 2015). "However, some studies have shown that rs2227485T>C in IL‐22 might be associated with an increased risk of papillary thyroid cancer and gastric mucosa‐associated lymphoid tissue lymphoma." (PMID 35808996, 2022). "Although IL-22 expression is reported to be elevated in many cancers, and increased IL-22 expression correlates with tumor progression and poor prognosis, little is known about the role of IL-22 in papillary thyroid cancer (PTC)." (PMID 31823782, 2019).
preeclampsia (3 papers, 2021 to 2025). Preeclampsia is a hypertensive disorder of pregnancy that is characterized by new-onset hypertension with proteinuria presenting after 20 weeks of gestation, and depending on mild or severe forms may initially present with severe headache, visual disturbances, and hyperreflexia. "Lower ratios of EV-encapsulated IL-17/TGF-β and IL-22/TGF-β would thus be associated with an increasing risk of preeclampsia." (PMID 36237987, 2022). "Reports of higher IL-22 concentrations in preeclampsia than in normal pregnancies further indicate the involvement of this axis in pathogenesis." (PMID 41156157, 2025). "During the third trimester, the concentration of placental small EVs and levels of two EV-encapsulated cytokines (IL21 and IL-22) were significantly higher in the preeclampsia patients." (PMID 36237987, 2022). "Using a diagnostic test assessment characteristic parameters (IL-22, MDC/CCL22, IL-2/IL-4 ratio) have been identified and cut-off values have been proposed to diagnose preeclampsia." (PMID 34248946, 2021). "Therefore, the aim of our study was to assess the population of Treg (CD4+CD25+FoxP3+) and Th17 lymphocytes, as well as the intracellular expression of IL-17A, IL-17F, IL-21, and IL-22 in women with PIH (including preeclampsia)." (PMID 41156157, 2025). "In light of the obtained data, the increased percentage of Th17 lymphocytes characterized by the simultaneous expression of IL-21 and IL-22 appears to be of particular importance, as it may constitute a potential immunological predictive marker for gestational hypertension." (PMID 41156157, 2025). "In the case of Th17 lymphocytes simultaneously expressing IL-21 and IL-22, a positive correlation was observed with maternal age (rho = 0.335; p = 0.0109), suggesting that this type of immune response may be more strongly represented in older pregnant women with gestational hypertension." (PMID 41156157, 2025). "During the second trimester, the total small EVs concentration and levels of three EV-encapsulated cytokines (IL-21, IL-22, and TGF-β) were significantly higher in the preeclampsia patients than in the healthy controls." (PMID 36237987, 2022). "In conclusion, we have demonstrated that a set of cytokines, IL-22, MDC, and IL-2/IL-4 can be used to diagnose preeclampsia, and what’s more to discriminate from gestational hypertension." (PMID 34248946, 2021). "The in-depth analysis showed that the IL-22, MDC, and IL2/IL-4 ratio can be used to discriminate between preeclampsia, gestation hypertension and healthy pregnancy." (PMID 34248946, 2021). "Regardless of the discrepancies, the analysis of a broad panel of 53 mediators suggests that IL-22, CCL22, and the IL-2/IL-4 ratio may aid in the diagnosis of PE and even in differentiating preeclampsia from gestational hypertension." (PMID 41156157, 2025).
relapsing-remitting multiple sclerosis (3 papers, 2014 to 2023). The most common clinical variant of multiple sclerosis, characterized by recurrent acute exacerbations of neurologic dysfunction followed by partial or complete recovery. "Overexpressed IRF4 in naive CD4+ T cells derived from relapsing remitting multiple sclerosis patients significantly increased their ability to secrete IL-17A, IL-17F, IL-21, and IL-22." (PMID 28808358, 2017). "In a human study, patients with relapsing-remitting multiple sclerosis (RRMS) were examined for IL-22 levels in their sera at various time intervals with or without treatment using interferon β-1a, interferon β-1b, and fingolimod." (PMID 37175665, 2023). "The plasma levels of IL-17 and IL-22 in GBS and relapsing-remitting multiple sclerosis at the acute phase of relapse were also markedly elevated." (PMID 24899787, 2014).
silicosis (3 papers, 2014 to 2025). Silicosis is a respiratory disease caused by breathing in (inhaling) silica dust. "The Th17 response is key to promoting silicosis inflammation and fibrosis by affecting the homeostasis of Th cell-mediated immune responses and increasing the production of IL-22 and IL-1β." (PMID 38515835, 2024). "IL-17 modulates the differentiation of Tregs in the early phase of silicosis and promotes the Th1/Th2 immune response, thus influencing silica-induced lung inflammation and fibrosis by regulating the production of IL-22 and IL-1β." (PMID 38515835, 2024). "In a future study, we plan to investigate the cross-talk between IL-22 and IL-17 in our silicosis model." (PMID 25091058, 2014). "IL-17 may promote lung inflammation by modulating the differentiation of Th1 and regulatory T cells (Tregs) and by regulating the production of IL-22 and IL-1β during the lung inflammation of silicosis." (PMID 25091058, 2014). "We speculated that increased IL-22 might contribute to a compensatory increase in Th22 cells, NK-22 cells and other cells in the IL-17-neutralized mice model of silicosis." (PMID 25091058, 2014). "In the present study, we demonstrated an increased IL-22 level in IL-17-neutralized silicosis mice." (PMID 25091058, 2014). "The Th17 response could induce lung inflammation during the pathogenesis of silicosis by regulating the homoeostasis of the Th immune responses and affecting the production of IL-22 and IL-1β." (PMID 25091058, 2014). "IL-17 neutralization may increase IL-22 expression in the lung inflammation of silicosis." (PMID 25091058, 2014).
skin changes (3 papers, 2011 to 2017). "The opposing effects of OSM and IL-1β compared with IL-17 and IL-22 on chemerin production in keratinocytes suggests different roles for the former in regulating chemerin-mediated skin changes." (PMID 25659101, 2015). "Deficiencies in either, IL-17 or IL-22 result in partial protection, whereas absence of both IL-17- and IL-22-mediated responses confers almost total protection against the disease, suggesting additive or synergistic effects of these cytokines in the development of skin changes." (PMID 25659101, 2015).
triple-negative breast carcinoma (3 papers, 2022 to 2025). An invasive breast carcinoma which is negative for expression of estrogen receptor (ER), progesterone receptor (PR), and human epidermal growth factor receptor 2 (HER2). "IL-22 enhances migration and maintains stemness in cancer cells across multiple cancer types, and IL-26 has been linked to EGFR-TKI resistance in triple-negative breast cancer." (PMID 40452847, 2025).